STAT3 (signal transducer and activator of transcription 3)
Diseases named in the same sentence as STAT3 in open-access papers (continued):
Sharing a sentence is not in itself a finding about the gene and the disease.
liver cancer (continued). "Moreover, NF- κB is known for its direct binding to other transcription factor such as STAT3 and its interaction promotes the development and progression of colon, gastric and liver cancers by regulating a number of cytokines and chemokines." (PMID 26998758, 2016). "To confirm this, we first examined whether LY5 inhibits constitutive STAT3 phosphorylation in colon and liver cancer cells." (PMID 26883202, 2016). "Our findings suggested that targeting Oct4/Nanog-mediated Stat3 signaling pathway may represent a novel approach to overcome EMT process in liver cancer cells displaying stem cell marker properties during tumor progression." (PMID 25879771, 2015). "In addition to NF-κB, other transcription factors, such as STAT3, have also been suggested to promote the development of liver cancer." (PMID 25360179, 2014). "In addition, activated IL-6/STAT-3 pathways have been observed in liver cancer and are thought to be important factors in the initiation, development, and progression of HCC." (PMID 24918094, 2014). "Notably, multiple transcriptional events have been identified in liver cancer, including NF-κB and STAT3." (PMID 25360179, 2014). "The present study shows that the knockdown of AEG-1 may inhibit cell proliferation and promote apoptosis in the liver cancer HepG2 cell line, and the molecular mechanism may involve the suppression of IL-6 secretion and the inhibition of Stat3 activation." (PMID 24348829, 2014). "Moreover, emerging evidence suggests that the cytokines downstream of STAT3 play an important role in the development of liver cancer." (PMID 22136659, 2011). "Our previous study on HCC specimens suggests an oncogenic role of STAT3 in liver cancer." (PMID 22136659, 2011). "Additionally, blockage of STAT3 using chemical inhibitors or siRNA induced liver cancer cell apoptosis and cell cycle arrest in vivo, and inhibited growth of transplanted liver cancer cells in vivo." (PMID 22136659, 2011). "The effects of STAT3 phosphorylation in liver cancer cells were also examined." (PMID 20712901, 2010). "Again, our data demonstrated that FLLL32 could efficiently inhibit STAT3 phosphorylation and induced apoptosis in four independent human liver cancer cell lines." (PMID 20712901, 2010). "Furthermore, Hu and associates showed that Metformin could enhance the sensitivity of liver cancer cells to Sorafenib via the ATF4/STAT3 signaling pathway." (PMID 40583627, 2025). "For instance, IL-6/JAK/STAT3 signaling enhances bladder cancer cell growth and is linked to targeted kinase inhibitor resistance, while TLR4 activation facilitates inflammation-associated carcinogenesis and liver cancer metastasis through protein tyrosine kinase 2 (PTK2) induction." (PMID 41573719, 2025). "Hence, inhibiting STAT3 is a possible anti-liver cancer therapeutic strategy." (PMID 38183094, 2024). "Then, it inhibits gene expression regulated by STAT3, downregulates gene expression related to cell proliferation, survival, apoptosis and invasion, activates apoptotic protein-3 and apoptotic protein-9, and thus promotes the dependent apoptosis of liver cancer cells." (PMID 36591515, 2022). "STAT3 inhibitors may be a potential option for liver cancer treatment." (PMID 35033067, 2022). "CircLRIG3 is significantly up-regulated in HCC, forming a ternary complex with EZH2 and STAT3, promoting EZH2-induced STAT3 methylation and subsequent phosphorylation, leading to the activation of STAT3 signal, thereby promoting the proliferation, migration, and invasion of liver cancer cells." (PMID 35463362, 2022). "Meanwhile, phosphorylation of STAT3 can bind directly to the promoter of the survivin gene, upregulate survivin expression and promote the survival of tumor cells; by inhibiting STAT3 activity, survivin gene expression can be downregulated to promote apoptosis of liver cancer cells." (PMID 34976809, 2021).
liver cancer (continued). "Activated STAT3 signals are associated with Twist and calcium adhesion protein E (E-cadherin) expression and mediate the invasion and metastasis of HCC cells, and an abnormal pSTAT3/Twist/E-cadherin signal axis leads to poor prognosis in patients with liver cancer." (PMID 34976809, 2021). "A previous study showed that lncRNA down-regulated in liver cancer stem cells (lncRNA DILC) regulated behaviors of liver cancer stem cells via IL-6/STAT3 axis, so we supposed that lncRNA DILC might be associated with the progression of neuropathic pain through regulating STAT3 activation." (PMID 32510145, 2020). "Therefore, increased HDAC3 enhanced tumor growth that may occur through STAT3 signaling in liver cancer cells." (PMID 29540666, 2018). "Furthermore, blockade of STAT-3 may have therapeutic potential in preventing and treating liver cancer." (PMID 24918094, 2014). "Blockage of STAT3 may have therapeutic potential in preventing and treating liver cancer." (PMID 22136659, 2011). "Thus, STAT3 in tumor infiltrating inflammatory cells may an attractive target for liver cancer therapy." (PMID 22136659, 2011). "A study discovered that STAT3 induces EMT and liver cancer metastasis by positively regulating TGF-β1." (PMID 40109873, 2025). "Together, these observations implicate age-associated expression of hepatocyte CD44, known for its role in liver cancer initiation, in activation of the immune suppressive IL6/JAK/STAT3 pathway and T cell dysfunction in the aged liver." (PMID 41509421, 2025). "By analyzing the common signaling pathways of STAT3 and FN1, their potential connection in liver cancer can be further revealed." (PMID 40772037, 2025). "In the context of liver cancer, GA additionally modulates the wnt/β-catenin and JAK/STAT3 signaling pathways, as well as their downstream molecular components." (PMID 40786042, 2025). "After identifying STAT3 and FN1 as hub genes for STA treatment of liver cancer, we performed single-gene analyses on these genes." (PMID 40772037, 2025). "In the field of liver cancer treatment, EGCG exhibits a triple effect, inhibiting tumor proliferation, invasion, and angiogenesis by downregulating the MAPK/AKT/STAT3 signaling cascade." (PMID 40218859, 2025). "Through in-depth studies of these pathways, a better understanding of the synergistic mechanisms of STAT3 and FN1 in liver cancer can be achieved, providing new targets and strategies for the treatment of liver cancer." (PMID 40772037, 2025). "After network pharmacology and single-gene analysis, we preliminarily identified STAT3 and FN1 as the molecular targets through which STA exerts its effect on liver cancer." (PMID 40772037, 2025). "In a complementary way, Urasaki and Le (2019) treated human liver cancer cells with CO, showing that the treatment upregulated the JAK/STAT signaling pathway by increasing the phosphorylation of STAT3." (PMID 38666018, 2024). "Following this, IL-6 activates the JAK/STAT3/Snail signaling axis, which leads to the depletion of the nuclear protein UHRF1, thereby inducing EMT in liver cancer cells." (PMID 38920657, 2024). "STAT3 decoy ODN reduced fibrosis and inflammatory factors in liver cancer cell lines and DDC-induced liver injury mouse model." (PMID 38338338, 2024). "In liver cancer, allicin (40 μM ) inhibits Cholangiocarcinoma (CCA) cell proliferation and invasion through STAT3 signaling—STAT3 is a key transcription factor involved in proliferation." (PMID 38542956, 2024). "To prove this hypothesis, we initially generated two liver cancer cell lines stably expressing STAT3 short hairpin RNA (shRNA) or control shRNA using a lentiviral transduction system and assessed the effect of STAT3 depletion on the expression of Pol III products by RT-quantitative PCR (qPCR)." (PMID 36656267, 2023).
liver cancer (continued). "Curcumol inhibited PD-L1 expression in liver cancer through crosstalk between HIF-1α and p-STAT3 (T705) signaling pathways, restoring cytotoxic T cell activity and the ability to kill tumor cells." (PMID 38155974, 2023). "Taken together, these results indicate that STAT3 can positively regulate Pol III-directed transcription in 293T and liver cancer cells." (PMID 36656267, 2023). "To assess the interplay of STAT1 and STAT3 protein in liver cancer cells, we first investigated the effect of STAT1 protein knockdown in the three liver cancer cell lines HepG2, HuH1, and HuH7, which all express the STAT1 and STAT3 proteins." (PMID 35267462, 2022). "Consistently, we found that endogenous PEG3 interacted with endogenous STAT3 in KTC primary cells and liver cancer PLCPRF5 cell line." (PMID 36451866, 2022). "Through the phosphorylation of transcription factors and STAT3, which enter the nucleus of liver cancer cells, CCT3 has an impact on the development of liver cancer in HCC." (PMID 36185198, 2022). "Caffeine and caffeic acid derivatives also act by inhibition of Akt, STAT3, p-ERK, p-FAK, and ROCK pathways in liver cancer cells." (PMID 36428575, 2022). "ZZXJD induced autophagy and apoptosis of liver cancer cells via inhibiting AKT/mTOR signaling pathway and JAK2/STAT3 signaling pathway, thereby affecting the growth and survival of liver cancer cells." (PMID 35432564, 2022). "In liver cancer, M1 macrophages secrete IL-35 to promote EMT through STAT3, and IL-35 leads to MET through M2 macrophage polarization, creating conditions for liver cancer progression." (PMID 35719927, 2022). "The signaling pathway is a significant contributor to liver cancer development and targeting the JAK/STAT3 signaling pathway is proposed as a promising therapy for HCC." (PMID 35439973, 2022). "In the cholangiocarcinoma and liver cancer model, SPRR2A is activated by STAT-3, promoting EMT through the interaction with ZEB1." (PMID 34934042, 2021). "The STAT3-mediated lncRNA HOXD-AS1 is upregulated by ceRNA and subsequently promotes the metastasis of liver cancer by regulating SOX4." (PMID 34101736, 2021). "Cheng et al43 reported that p120‐catenin (p120ctn) present in exosomes secreted by liver cancer cells inhibited the growth of liver cancer stem cells and the proliferation and metastasis of HCC cells through the STAT3 pathway." (PMID 33247543, 2021). "OF activates phosphorylation of STAT3 and enhances the binding to P1‐promoter of HNF4A which is the potential mechanism for reducing hepatocarcinogenesis in liver cancer." (PMID 33377648, 2020). "In summary, these results suggest that, in liver cancer cells, DNMT3a upregulation promotes SOCS3 promoter methylation and suppresses SOCS3 expression, which further activates JAK2/STAT3 signaling pathway." (PMID 33234142, 2020). "Taken together, QE inhibited the progression of liver cancer, at least partially, by inhibiting the activation of JAK2/STAT3 signaling pathways." (PMID 31273958, 2019). "In liver cancers, SHP1 is downregulated in cells with mesenchymal features, and restoring its levels both reduced STAT3 phosphorylation and reversed the mesenchymal phenotype of liver cancer cells." (PMID 31557897, 2019). "The stem cell properties of CD90+ liver cancer cells are regulated by the downstream SHH/Gli and IL6/JAK2/STAT3 signalling pathways." (PMID 29722127, 2018). "In gastric and liver cancers, miR-375 functions through the JAK2/STAT3 signaling pathway to control cell proliferation and apoptosis." (PMID 28186962, 2017). "Above all, the Stat3–Sox4 signalling plays an indispensable role in liver TIC self-renewal, liver cancer initiation and propagation." (PMID 27553854, 2016).
liver cancer (continued). "In this direction, we examined the expression of inflammatory proteins IL6, STAT3, TNF-α and NF-κB in hepatic cancer tissues." (PMID 27760163, 2016). "Persistent STAT3 phosphorylation in SSMC 7721, Huh7, HEPG2, and Hep3B liver cancer cell lines were inhibited after treatment with LY5 for 24 hours." (PMID 26883202, 2016). "In this article, the authors show that a previously unidentified lncRNA, LncSox4, is highly expressed in liver cancer TICs and regulates TIC self-renewal through the Stat3/SOX4 axis." (PMID 27553854, 2016). "A higher state of inflammation was observed in liver cancer tissues as evident from upregulation of inflammatory cytokines IL-6 and TNF-α along with NF-κB and STAT3." (PMID 27760163, 2016). "The expression of STAT3 target genes, Survivin, Bcl-2 and Bcl-xl, were decreased in SSMC 7721, Huh7, HEPG2 and Hep3B liver cancer cells after treatment with LY5 as examined by Western Blot." (PMID 26883202, 2016). "We proved that the Stat3–Sox4 pathway participates in liver tumorigenesis and liver TIC self-renewal, thus offering a new potential target of TICs for eradicating liver cancer." (PMID 27553854, 2016). "NNMT promoter activity has also been correlated to the activation of signal transducer and activator of transcription 3 (STAT3) in colorectal tumor tissues and Hep G2 liver cancer cells stimulated with interleukin (IL)-6." (PMID 23990942, 2013). "FLLL32 has little effect in inhibiting STAT3 S727 phosphorylation in SNU449, HEP3B, SNU398 and liver cancer cells lines." (PMID 20712901, 2010). "For example, STAT3 upregulates the expression of vascular endothelial growth factor (VEGF), promoting tumor angiogenesis and ensuring an adequate supply of nutrients and oxygen for liver cancer cells." (PMID 41280670, 2025). "In TCGA liver cancer data, we found a positive correlation between the expression of FN1 and STAT3." (PMID 40772037, 2025). "For example, the PI3K-Akt and JAK-STAT signaling pathways may be key pathways in which STAT3 and FN1 are jointly involved, playing significant roles in the occurrence and development of liver cancer." (PMID 40772037, 2025). "Therefore, our findings suggested that reduced SOCS3 expression coupled with enhanced STAT3 phosphorylation activated the IL6/JAK/STAT signaling pathway, resulting in an elevated incidence of primary liver cancer in FXR−/− mice." (PMID 39940889, 2025). "In the current study, FPHPE was found to inhibit the growth of HCC by reducing the phosphorylation of JAK2 and STAT3 and preventing STAT3 from going into the nucleus, suggesting that FPHPE alleviated the inflammatory signaling of liver cancer by targeting the JAK2/STAT3 pathway." (PMID 41200213, 2025). "Although STAT3 and FN1 play different roles in liver cancer, there may be some connection between them." (PMID 40772037, 2025). "Additionally, curcumol suppressed PD-L1 expression in hepatic cancer by interfering with the HIF-1α and p-STAT3 (T705) signaling pathways." (PMID 39690423, 2024). "Morusin, a flavonoid isolated from Morus alba (mulberry tree), has demonstrated potent anti-cancer properties by inhibiting key oncogenic pathways such as nuclear factor kappa B (NF-κB) and signal transducer and activator of transcription 3 (STAT3) in prostate, pancreatic, and liver cancers." (PMID 39650709, 2024). "The objective is to explore whether K73-03 could induce apoptosis or autophagy in liver cancer cells and clarify its relationship with JAK2 / STAT3 signaling pathway or other possible mechanisms." (PMID 38185661, 2024). "Moreover, liver cancer cells further demonstrate that SAMA also suppresses the signal transducer and activator of transcription 3 (STAT3) activation." (PMID 38399445, 2024). "In uterine sarcoma and liver cancer, RACGAP1 activated the STAT3-survivin signaling pathway." (PMID 37196108, 2023). "Indeed, it has been shown that in breast and liver cancer, STAT5 signaling can offset the oncogenic effects of STAT3." (PMID 37369132, 2023).
liver cancer (continued). "Through the preliminary RNA-seq analysis, combined with the Western blot and qRT-PCR detection of this experiment, the research team found that the prescription ZZXJD inhibited the proliferation of liver cancer cells and was related to the PI3K/Akt/m TOR and JAK2/STAT3 signaling pathways." (PMID 35432564, 2022). "LncRNA down-regulated in liver cancer stem cells (lnc-DILC) has an inhibitory role in liver cancer stem cells’ self-renewal and suppresses its expansion by down-regulation of IL-6 transcription and STAT3 activation." (PMID 36207500, 2022). "Depending on STAT3, HBX promotes the expression of HMGB1 to enhance EMT in liver cancer cells." (PMID 35251017, 2022). "Moreover, under hypoxia, phosphorylated STAT3 enhances HIF1α stability to increase HIF1α-mediated VEGF secretion, promoting angiogenesis in renal carcinoma and liver cancer." (PMID 35123491, 2022). "In line with this, recent studies have shown that simvastatin, a potent HMGCR inhibitor, induces apoptosis and cell cycle arrest by activating AMPK and inhibiting the Signal Transducer and Activator of Transcription 3 (STAT3) axis, both in liver cancer cells and tumor xenografts." (PMID 33718197, 2021). "Overall, consideration of the IL-6/STAT3 signaling pathway, and its role in the carcinogenesis and progression of HCC will contribute to the development of potential drugs for targeting treatment of liver cancer." (PMID 34976809, 2021). "In liver cancer, IRF2 can inactivate the STAT3 signaling pathway." (PMID 34022918, 2021). "Using liver cancer cell lines and subcutaneous mice models, we demonstrated that Kyn produced by TDO2/Trp metabolism activated AhR/IL-6 pathway in liver cancer, eventually resulting in upregulation of the NF-kB/TIM4/STAT3 signals and cancer development." (PMID 34657635, 2021). "The INPP5F gene product negatively regulates the STAT3 signaling pathway by inhibiting phosphorylation of STAT3 but the functional role of the gene in primary liver tumor pathogenesis has not been characterized." (PMID 31796844, 2019). "As the up-stream of STAT3, inhibition the binding of IL-6 and GP130 may also exhibit potent growth-suppressive activity in liver cancer cells." (PMID 28430601, 2017). "Additionally, IL-6 induced STAT3 phosphorylation in the nucleus, which was blocked by LY5 pre-treatment in Hep3B liver cancer cells." (PMID 26883202, 2016). "Moreover, B7-H1 expression by liver cancer cells correlated with TAM infiltration in HCC tissue and was dependent on IL-10-induced NF-κB an STAT-3 signaling pathways." (PMID 23533994, 2013). "Elucidating the roles STAT3 in HBV infection and HBV inducing neoplastic transformation will shed light on the molecular basis of liver cancer and may suggest therapeutic strategies for this severe disease." (PMID 22136659, 2011). "The constitutive activation of STAT3 is frequently detected in clinical incidences of liver cancer and in more than 50% of human liver cancer cell lines but not in normal or non-transformed human cells." (PMID 20712901, 2010). "FLLL32 inhibit STAT3 Y705 phosphorylation in SNU449, HEP3B, SNU387, and SNU398 liver cancer cells." (PMID 20712901, 2010). "However, the role of the AKT/mTOR/STAT3/ID1 axis in liver cancer remains unexplored, and the effects of therapeutics targeting the AKT/mTOR/STAT3/ID1 signaling pathway remain unknown." (PMID 38183094, 2024). "NF-kb and STAT3 play an important role in the development and regulation of liver cancer, so we used the complementary DNA (cDNA) prepared from total RNA to examine the methylation activity in the coding sequences of NF-kb and STAT3 in rats with HCC compared to the negative control." (PMID 38322013, 2023). "Additionally, a methylation study of liver cancer indicated that low expression of IL-6 can reduce angiogenesis in HCC tissues, suggesting that the IL-6/STAT3 signaling pathway can promote angiogenesis in tumor tissues and provide nutrient guarantees for the development of tumorigenesis." (PMID 34976809, 2021).